RNY3P10 (RNY3 pseudogene 10)
Gene: Miscellaneous RNA gene on chromosome 13 (69,802,940 to 69,803,041, forward strand). Ensembl gene ENSG00000207495.
Homologues: Orthologues: chimpanzee Y_RNA (97% identical), macaque Y_RNA (88% identical). Paralogues in human: Y_RNA (86% identical), Y_RNA (85% identical), RNY3 (84% identical), Y_RNA (84% identical), RNY3P1 (83% identical), Y_RNA (83% identical), RNY3P9 (82% identical), Y_RNA (82% identical), RNY3P11 (81% identical), RNY3P5 (81% identical), Y_RNA (81% identical), RNY3P14 (80% identical), and 93 more.